LAMA2 (laminin subunit alpha 2)
Diseases named in the same sentence as LAMA2 in open-access papers (continued):
Sharing a sentence is not in itself a finding about the gene and the disease.
muscular dystrophy (continued). "The pathology of LAMA2 MD patients is dominated by an early-onset, severe muscular dystrophy that ultimately leads to death by respiratory insufficiency." (PMID 37038437, 2023). "For example, AD, PD, and MND were all associated with SNPs in LAMA2, PTPN12, and SPATA7, which are implicated in muscular dystrophy, colon cancer, and retinitis pigmentosa, respectively." (PMID 35711735, 2022). "This study provides better understandings of natural history and genotype–phenotype correlations in LAMA2-related muscular dystrophy, and supports therapeutic targets for future researches." (PMID 34281576, 2021). "Even though, epilepsy should be monitored, especially in older children with LAMA2-related muscular dystrophy." (PMID 34281576, 2021). "Although there are a few retrospective, cross-sectional studies exploring the natural history and genetic variations of LAMA2-related muscular dystrophy, long-term and large-scale studies of the natural history and genotype–phenotype correlations are limited." (PMID 34281576, 2021). "Our purpose was to identify valid and reliable information of the natural history and genotype–phenotype correlations of LAMA2-related muscular dystrophy." (PMID 34281576, 2021). "Brain MRIs of 53 LAMA2-related muscular dystrophy patients were reassessed, occipital pachygyria (18.7%, 10/53) and pontine hypoplasia (15.1%, 8/53) were found." (PMID 34281576, 2021). "Potential therapeutic interventions including splice modulation, upregulation of the LAMA1 gene, mini-agrin and αLNNd are in development for LAMA2-related muscular dystrophy." (PMID 34281576, 2021). "In this study, we designed a large national multicenter study of LAMA2-related muscular dystrophy patients in the Chinese population." (PMID 34281576, 2021). "LAMA2-related muscular dystrophies represent one of the most common forms of human CMD world-wide, so it seems possible that this form of CMD occurs more commonly in dogs but is not clinically recognized and underdiagnosed." (PMID 34828429, 2021). "Here, we report a comprehensive natural history and genetic analysis in the largest LAMA2-related muscular dystrophy cohort thus far, to address clinical and genotypic predictors of phenotypes and disease progression." (PMID 34281576, 2021). "We aimed to describe the natural history and establish genotype–phenotype correlations in a large cohort of Chinese patients with LAMA2-related muscular dystrophy." (PMID 34281576, 2021). "Limitations: This study has provided useful data regarding natural history and genetic features of LAMA2-related muscular dystrophy with some limitations." (PMID 34281576, 2021). "In summary, in the current study, the natural history and genetic features of LAMA2-related muscular dystrophy were characterized." (PMID 34281576, 2021). "The study provides important information and basis for differentiating LAMA2-related muscular dystrophy subtypes and different focus of multidisciplinary management of LAMA2-related muscular dystrophy subtypes." (PMID 34281576, 2021). "Clinical and genetic data of LAMA2-related muscular dystrophy patients enrolled from ten research centers between January 2003 and March 2021 were collected and analyzed." (PMID 34281576, 2021). "LAMA2-related muscular dystrophy including LAMA2-related congenital muscular dystrophy (LAMA2-CMD) and autosomal recessive limb-girdle muscular dystrophy-23 (LGMDR23) is caused by LAMA2 pathogenic variants." (PMID 34281576, 2021). "Muscle regeneration, inflammation and fibrosis are tightly connected in muscular dystrophy and this venue has, to some extent, been explored in mouse models for LAMA2-CMD." (PMID 32457577, 2020). "LAMA2-related muscular dystrophy has, at its root, chronic dysregulated remodeling of the myomatrix." (PMID 32116541, 2020). "We further show that separate treatment with two antioxidant drugs (both approved for human use) prevents muscular dystrophy progression in the dy2J/dy2J mouse model of LAMA2-CMD." (PMID 32197453, 2020).
muscular dystrophy (continued). "In this review, we mainly focus on impaired regeneration and SC involvement in the pathology of muscular dystrophies and the new findings in LAMA2-CMD." (PMID 32523512, 2020). "The Lama2 (dyW) mice recapitulate the clinical manifestations of MDC1A patients and display severe muscular dystrophy, with death around 5–7 weeks of age." (PMID 33138863, 2020). "Since inflammation is recognized as a critical driver of disease pathology in many muscular dystrophies including LAMA2-CMD, we assessed the inflammatory response in treated and non-treated animals." (PMID 32197453, 2020). "This review will mainly focus on SC contribution to impaired regeneration in muscular dystrophies and specifically new findings suggesting SC involvement in LAMA2-CMD pathology." (PMID 32523512, 2020). "The laminin α2–related muscular dystrophies (LAMA2-RDs) are a subtype of congenital muscular dystrophy (CMD) caused by recessive variants in the LAMA2 gene [6q22–q23; OMIM*156225]." (PMID 32848593, 2020). "This disorder is referred to as LAMA2-MD (LAMA2 gene Muscular Dystrophy) and also as MDC1A (Muscular Dystrophy Congenital type 1A)." (PMID 31920536, 2019). "An identical homozygous duplication of exon 30 in LAMA2 was found in two seemingly unrelated individuals of the same ethnic origin (RD_P394, RD_P395) with muscular dystrophy." (PMID 31694722, 2019). "One of the main traits of LAMA2-CMD (as well as other types of muscular dystrophy) is the build-up of fibrotic tissue, which gradually replaces muscle." (PMID 28771630, 2017). "Previously, it has been shown that complete knockout of Lama2 in mice resulted in a generalized growth retardation and severe muscular dystrophy and death by 5 weeks of age suggesting similar pathological processes being altered in all vertebrate models." (PMID 22952766, 2012). "Moreover, skeletal muscle regeneration in mice with laminin-α2 (LAMA2)-related muscular dystrophy is severely impaired and restoring the connection to the basal-lamina using linker-molecules is able to partially reverse this phenotype." (PMID 41550718, 2026). "Currently, there are no effective treatment methods for LAMA2-associated muscular dystrophy, although active research is underway to develop gene therapy." (PMID 39941024, 2025). "Then, we conducted single-cell RNA sequencing (scRNA-seq), RNA sequencing, western blot, and immunofluorescence to provide more useful data and information for further investigating the molecular pathogenetic mechanisms of muscular dystrophy and brain dysfunction for LAMA2-CMD." (PMID 40960171, 2025). "Therefore, LAMA2-related muscular dystrophy (MD) is generally divided into MDC1A (also named LAMA2-CMD, the severe one) and LGMDR23(the mild one) categories." (PMID 37404563, 2023). "It is of course possible that the treatment of the LAMA2 MD patients and the subsequent amelioration of the muscular dystrophy by the linker proteins may make the peripheral neuropathy more apparent." (PMID 37038437, 2023). "LAMA2 is the causative gene of autosomal recessive limb-girdle muscular dystrophy-23 (OMIM #618138) and congenital merosin deficient or partially deficient muscular dystrophy (OMIM #607855), in which epilepsy was regarded as one of the core features." (PMID 35663266, 2022). "LAMA2 (OMIM:156225) is considered to produce muscular dystrophy with very few ocular features." (PMID 35457050, 2022). "Interestingly, it has been shown that laminin 111 is able to reduce pathology in mouse models of Duchenne and LAMA2-related muscular dystrophy." (PMID 36523505, 2022). "LAMA2-related muscular dystrophy shows a spectrum of clinical manifestations ranging from comparably mild late onset forms in adulthood to conditions that manifest in neonates, leading to severe muscle wasting accompanied by a broad spectrum of secondary effects such as spinal deformities." (PMID 36523505, 2022).
muscular dystrophy (continued). "Compared with non-ambulatory LAMA2-related muscular dystrophy patients, epilepsy was associated with the ambulatory group (p = 0.008)." (PMID 34281576, 2021). "We also found that LAMA2-CMD was related to nonsense variants, LAMA2-related muscular dystrophy with nonsense variants such as c.7147C > T (p.R2383*) might benefit from the stop codon readthrough." (PMID 34281576, 2021). "Twenty-four LAMA2-related muscular dystrophy patients died, mostly due to severe pneumonia." (PMID 34281576, 2021). "Recently, two natural history studies on 46 LAMA2-related muscular dystrophy pediatric patients in the Dubowitz Neuromuscular Centre and 24 LAMA2-related muscular dystrophy patients in National Institutes of Health provided useful information towards trial readiness." (PMID 34281576, 2021). "The prototype of LAMA2-RD was first reported in mice of the Bar Harbor 129 Re strain in 1955 (dystrophic mice Lama2dy/dy); this was however limited to the recessive inherited muscular dystrophy phenotype." (PMID 32390798, 2020). "Hence, the mouse models still offer the best chance for important discoveries and preclinical studies for muscular dystrophies like LAMA2-CMD will certainly remain fully dependent on animals." (PMID 32457577, 2020). "Mutations in this gene have been reported to cause muscular dystrophy, but thus far no studies have elucidated the role of LAMA2 in the fate choices of MSCs." (PMID 32213190, 2020). "Interestingly, one of the remaining tumors has a deletion in LAMA2, bringing the number of ONBs with deletions of genes involved in the development of muscular dystrophies to 13 or 93%." (PMID 30575736, 2018). "The LAMA2 gene is associated with muscular dystrophy, although it is not described in any public database." (PMID 30231296, 2018). "Firstly, this study only included 5 patients, which may lead to insufficient statistical power and limited representativeness, influencing to support the clinical heterogeneity of LAMA2-MD (LAMA2-related muscular dystrophy) and the rules of genotype–phenotype correlation." (PMID 41567540, 2025). "Mutations in the alpha-2 subunits of the Laminin (LAMA2) gene result in the deficiency of a key structural skeletal muscle protein known as merosin and cause an autosomal recessive congenital muscular dystrophy (CMD) subtype known as the laminin a2-related muscular dystrophies (LAMA2-RD)." (PMID 38975466, 2024). "Hence, besides the treatment of the muscular dystrophy, early treatment of LAMA2 MD patients may also prevent a possible axonal sorting defect." (PMID 37038437, 2023). "However, in contrast with other muscular dystrophies, inflammatory infiltrate is decreased during later stages of LAMA2-CMD muscle disease progression and its role in LAMA2-CMD muscle disease remains unclear." (PMID 32498713, 2020). "LAMA2‐related muscular dystrophy (LAMA2 MD) is a significant subtype of CMD, which encompasses a group of early‐onset muscular dystrophies." (PMID 39949979, 2025). "Even in the largest and multicenter research of LAMA2-related muscular dystrophy in 2021, 14 cases of LGMDR23 were reported while 116 cases of MDC1A were reported." (PMID 37404563, 2023). "Interestingly, fibroblasts cultured from one patient with a LAMA2-related muscular dystrophy exhibited reduced COLVI secretion, although no mutations were found in their COL6A1-3 genes, suggesting the important role of extracellular matrix homeostasis in skeletal muscle health." (PMID 34066978, 2021). "Congenital muscular dystrophy type 1A (LAMA2-CMD) is a severe, recessive autosomal form of muscular dystrophy." (PMID 32197453, 2020). "We studied the LAMA2 and SGCG genes responsible for the MDC1A and LGMD2C forms of muscular dystrophies, respectively." (PMID 21637626, 2010).
muscular dystrophy (continued). "This study has provided potentially important information for the molecular pathogenetic mechanisms of muscular dystrophy and brain dysfunction for LAMA2-CMD, however, some related functional experiments have not been further performed." (PMID 40960171, 2025). "LAMA2-CMD is a common form of CMD and accounts for 24–37% of all congenital muscular dystrophies." (PMID 37206914, 2023). "The relationship between the common variants in LAMA2, DAG1 and ITGA7 that are associated with myopia and the mutations in these same genes causing muscular dystrophy is not clear." (PMID 36737489, 2023). "While these genes have not been described in the context of muscular dystrophies, their downregulation suggests that LAMA2 Ex3 KO may influence ribosomal function and cell metabolism in myogenic precursors." (PMID 41309582, 2025). "This suggests that in contrast with other muscular dystrophies, the immune system in LAMA2-CMD may not play a major role in later stages of disease progression." (PMID 32498713, 2020). "Finally, we show that intramuscularly injected AAVMYO delivers transgenes to muscle-residing mononuclear cells in the dyW/dyW mouse model of LAMA2-related muscular dystrophy, demonstrating that these cells can be targeted to express therapeutic transgenes in the context of muscular diseases." (PMID 40225019, 2025). "Hence, there is evidence that LAMA2 MD is not a pure muscular dystrophy." (PMID 37038437, 2023). "It was worth mentioning that 5/9 LAMA2-CMD patients with epilepsy and all three LGMDR23 patients with epilepsy showed their first epileptic episode after age of 10 years, indicating that epilepsy might be more frequent in older children with LAMA2-related muscular dystrophy." (PMID 34281576, 2021). "In LAMA2-CMD, unlike other muscular dystrophies, the inflammatory infiltrates peak early and decline during the later stages." (PMID 40161708, 2025).
congenital muscular dystrophy (88 papers, 2005 to 2025). A muscular dystrophy that is characterized by diminished muscle tone (hypotonia), progressive muscle weakness and degeneration (atrophy), abnormally fixed joints, spinal rigidity, and delays in reaching motor milestones such as sitting or standing unassisted. "LAMA2-related muscular dystrophy (LAMA2 MD or MDC1A) is a devastating congenital muscular dystrophy caused by mutations in the LAMA2 gene." (PMID 41309582, 2025). "In humans, mutations to LAMA2 can lead to congenital muscular dystrophy characterised by muscle weakness, respiratory problems and delayed motor development." (PMID 39286762, 2024). "Mutations in the Laminin-α2 gene determine the LAMA2-deficient congenital muscular dystrophy (LAMA2-CMD), an irreversible degenerative muscle disease leading to muscle weakness, neuropathy, and hypotonia in the lower limbs." (PMID 38891777, 2024). "Recessive pathogenic variants in the laminin subunit alpha 2 (LAMA2) gene cause a spectrum of disease ranging from severe congenital muscular dystrophy to later-onset limb girdle muscular dystrophy (LGMDR23)." (PMID 36779065, 2023). "Mutations within the Lama2 gene coding for the Lmα2-subunit cause as much as 30% of cases of congenital muscular dystrophy (CMD)." (PMID 36878377, 2023). "Null mutations of the Lama2-gene cause a severe congenital muscular dystrophy and associated neuropathy." (PMID 36878377, 2023). "The mutations in the LAMA2 gene caused congenital muscular dystrophy (CMD), an autosomal recessive disorder." (PMID 37404563, 2023). "Recently, a novel frameshift homozygous variant (p.Tyr1313LeufsTer4) in the LAMA2 gene was found in a patient with congenital muscular dystrophy who had autism-like behavior." (PMID 37511534, 2023). "The laminin alpha 2 chain is encoded by the LAMA2 gene, which is also related to hip dysplasia and cartilage development and is thought to contribute to congenital muscular dystrophy." (PMID 37612746, 2023). "LAMA2-related muscular dystrophy (LAMA2 MD or MDC1A) is a devastating congenital muscular dystrophy that is caused by mutations in the LAMA2 gene encoding laminin-α2, the long chain of several heterotrimeric laminins." (PMID 37038437, 2023). "Congenital muscular dystrophy caused by merosin/laminin α2 chain deficiency (MDC1A) is due to a mutation in the gene coding for the α2 subunit of the Laminin gene (LAMA-2)." (PMID 36613804, 2022). "Most studies focused on LAMA2 deficiency leading to muscular disease, and it is known that mutations in LAMA2 produce a particularly severe type of congenital muscular dystrophy, called LAMA2 chain deficient congenital muscular dystrophy (LAMA2-CMD)." (PMID 36357874, 2022). "In particular, mutations in LAMA2 result in a type of muscular congenital dystrophy: the “Laminin-α2 chain-deficient congenital muscular dystrophy” or “LAMA2-CMD”29,30." (PMID 33469097, 2021). "MDC1A is an autosomal recessive disease which occur by mutations in LAMA2 gene and represents the predominant subtype of congenital muscular dystrophy." (PMID 34528292, 2021). "Loss-of-function mutations in the LAMA2 gene are the most common cause of severe LAMA2-related congenital muscular dystrophy (LAMA2-CMD)." (PMID 32116540, 2020). "A case study using biopsies from congenital muscular dystrophy patients with laminin-α2 chain deficiency showed reduced integrin-α7B expression in the sarcolemma of six LAMA2-CMD patients." (PMID 32116540, 2020). "A complete loss of laminin-211, which is encoded by LAMA2, causes a severe congenital muscular dystrophy with onset of symptoms in the first few months of life." (PMID 31133972, 2019). "Deficiency of laminin α2 chain leads to a severe form of congenital muscular dystrophy (LAMA2-CMD), and dystrophic symptoms progress rapidly in early childhood." (PMID 31586140, 2019). "Congenital muscular dystrophy with laminin α2 chain-deficiency (LAMA2-CMD) is a severe muscle disorder with complex underlying pathogenesis." (PMID 30389963, 2018).